EZH2 (enhancer of zeste 2 polycomb repressive complex 2 subunit)
Diseases named in the same sentence as EZH2 in open-access papers (continued):
Sharing a sentence is not in itself a finding about the gene and the disease.
tumor (continued). "The genes EZH2 was significantly higher expressed in tumor tissue while SCP2, ALDH3A2, and PRKAA2 were significantly upregulated in normal tissue." (PMID 40271062, 2025). "Recent studies have shown that EZH2 contributes to tumor immune evasion by trimethylation of lysine 27 of histone H3 (H3K27me3) on the B2m promoter in cancer cells." (PMID 41252204, 2025). "The development of various cancers seems to be influenced by EZH2 dysregulation because it leads to tumor‐suppressor gene silencing." (PMID 40959208, 2025). "For example, OGG1 recruits chromodomain helicase DNA binding protein 4 (CHD4) and enhancer of zeste homolog 2 (EZH2) to sites of 8-oxoG formation in promoters of tumor suppressor genes." (PMID 41465236, 2025). "Targeting EZH2 suppresses tumor growth, enhances radiation sensitivity, and disrupts GSC maintenance, making it a promising therapeutic approach." (PMID 40628732, 2025). "Recent findings have revealed that the PRC2/EZH2 complex, in addition to its well-established canonical function in chromatin repression, further exerts a regulatory effect on tumor immunity." (PMID 41335282, 2025). "We elucidated the mechanisms by which squamocin induces ER stress, leading to ER‐associated degradation (ERAD) of EZH2 and MYC proteins, ultimately resulting in tumor growth arrest." (PMID 39823459, 2025). "EZH2 is overexpressed or dysfunctional in numerous types of cancer, and EZH2 inhibitors exert their anti-tumor effects by blocking its methyltransferase activity, thereby reactivating silenced genes." (PMID 40032852, 2025). "The authors identified distinct acquired mutations which converges on the RB1/E2F axis and result in decoupling of EZH2-dependent differentiation and cell cycle control, allowing tumour cells to escape tazemetostat-induced G1 arrest." (PMID 40011240, 2025). "Along with EZH2 downregulation, the trimethylation level of histone H3 lysine 27 in Usp22-null tumor cells was reduced." (PMID 41252204, 2025). "By targeting the EZH2-PD-L1 axis, Capsanthin not only inhibits tumor progression but also potentially enhances anti-tumor immune responses." (PMID 40038276, 2025). "Given MDSC-mediated tumor immunosuppression, clinical use of EZH2 inhibitors must be approached with caution." (PMID 40042761, 2025). "Collectively, these findings demonstrate that squamocin suppresses tumor growth primarily in an EZH2‐dependent manner in HNSCC." (PMID 39823459, 2025). "The EZH2 inhibitor CPI-1205 reprograms tumor-infiltrating Tregs into a pro-inflammatory Th1-like phenotype." (PMID 39858465, 2025). "In our previous studies, we found that AQB, a small molecule drug targeting HOTAIR and EZH2, restores the expression of multiple tumor suppressor genes and inhibits EC progression, demonstrating significant antitumor activity and a favorable safety profile." (PMID 41353219, 2025). "Hypoxia-activated XBP1 recruits EZH2 to the promoter of tumour suppressor genes, thereby favouring BC metastasis." (PMID 40968252, 2025). "By silencing tumor suppressor genes, EZH2 enhances cell proliferation, invasion, and progression of cancer cells 84-90." (PMID 40959108, 2025). "Our comprehensive work complements the existing research on PRC2, particularly the extensively studied EZH2 subunit, which is known for its involvement in the epigenetic silencing of tumor suppressor genes and promotion of cancer progression." (PMID 39791545, 2025). "VPA–NaDCA and TMZ reduced the invasion of U87 and T98G tumors, as well as the expression of PCNA and EZH2 in the tumor." (PMID 40725030, 2025). "Combining DNMT and HDAC inhibitors with other targeted therapies like EZH2 inhibitors can synergistically restore normal gene function and inhibit tumor growth by reactivating tumor‐suppressor genes and modulating signaling pathways." (PMID 40959208, 2025). "EZH2 overexpression is positively correlated with tumour size, lymphatic invasion, and poor patient outcomes." (PMID 41614754, 2025).
tumor (continued). "EZH2 is upregulated in tumor tissues of HCC patients, influencing transcription at the epigenetic level and promoting the progression of HCC." (PMID 39850359, 2025). "To validate the elevated expression of EZH2 protein in TCL, we compared the EZH2 expression levels between tumor cell lines and normal T cells." (PMID 40659662, 2025). "Consistent with the in vitro findings, overexpression of EZH2 resulted in a significant promotion in tumor volume and weight, which were effectively abrogated by treatment with EPZ‐6438 or squamocin." (PMID 39823459, 2025). "Immunohistochemical (IHC) analysis from the Human Protein Atlas further confirmed the increased EZH2 protein expression in tumor samples." (PMID 41209556, 2025). "Elevated EZH2 expression is known to promote tumor progression by suppressing apoptosis and enhancing cell cycle progression." (PMID 40074445, 2025). "The overexpression of EZH2 and increased H3K27me3 have been correlated with tumor progression and poor prognosis in OSCC." (PMID 40427514, 2025). "When upregulated, LINC-PINT inhibits tumour growth and migration by recruiting EZH2, leading to H3K27 trimethylation and epigenetic silencing of target genes." (PMID 41463281, 2025). "In normal cells, EZH2 helps maintain genomic stability and prevent inappropriate cell division, acting as a tumor suppressor." (PMID 40723311, 2025). "WDR5–MYC complexes drive super-enhancer formation at oncogenic loci, whereas EZH2-mediated PRC2 activation silences tumor suppressors such as CLU and CADM1." (PMID 40787450, 2025). "Overexpression of EZH2 and excessive H3K27 trimethylation have been linked to aggressive tumor behavior in PDEECs by silencing tumor suppressor genes and maintaining cells in an undifferentiated state." (PMID 40072110, 2025). "Histone methylation, often mediated by histone methyltransferases (HMTs) like EZH2, results in chromatin compaction, silencing tumor‐suppressor genes by adding methyl groups to specific lysine residues on histones." (PMID 40959208, 2025). "Mutations in the SMARCB1 tumour suppressor gene led to the development of epithelioid and rhabdoid sarcomas, and loss of SMARCB1 upregulates the expression of EZH2." (PMID 40011240, 2025). "The elevated activity of EZH2 enhances H3K27 methylation which leads to the silencing of tumor‐suppressor genes." (PMID 40959208, 2025). "miR-101 has been reported to upregulate EZH2 and thereby promote tumor growth, invasion, angiogenesis, and chemoresistance, whereas miR-137 and miR-138 downregulate EZH2, suppressing the malignant phenotype." (PMID 40450300, 2025). "In this study, we investigated the role of EZH2 in CRC by assessing its expression in tumor tissues and cell lines, evaluating its effects on cell proliferation and chemoresistance, and exploring its influence on autophagy." (PMID 40314246, 2025). "The concurrent downregulation of BRN2 (91.4%) and EZH2 (89.5%) by HOC treatments underscores a potent suppression of this oncogenic transcriptional axis in NCI-H660 tumor cells." (PMID 41514539, 2025). "Inhibitors of EZH2 have shown potential in reducing tumor growth and enhancing the efficacy of immune checkpoint inhibitors (ICIs) like anti-PD-1/PD-L1 antibodies in various cancers." (PMID 40038276, 2025). "MiR-200c that function as a tumor suppressor gene regulates methotrexate sensitivity through inhibiting the expression of EZH2 and elevating the expression of E-cadherin." (PMID 40701777, 2025). "Among the genes commonly occupied by ERα and EZH2, the tumor suppressor BTG2 was selected for validation, based on its crucial role as cancer antagonist." (PMID 39922814, 2025). "Although inhibitors targeting SETD2 (e.g., EZM0414) and EZH2 (e.g., tazemetostat) demonstrate antitumor activity in preclinical models, their clinical efficacy remains constrained by drug resistance and tumor microenvironment heterogeneity." (PMID 40959108, 2025).
tumor (continued). "Previous studies in tumor cells have shown that MELK can phosphorylate downstream regulatory proteins such as EZH2 and ASK1, thereby altering the activity of major signaling pathways." (PMID 41278210, 2025). "EZH2 catalyzes tri-methylation of histone H3 at Lys27 (H3K27me3) and has a role in epigenetic activation and silencing of key oncogenes and tumor suppressor genes in multiple cancers as well as contributing to drug resistance." (PMID 40138429, 2025). "Long-chain non-coding RNA (lncRNA) can regulate gene expression at multiple levels and is related to the function of EZH2 and its maintenance of high expression in tumor cells." (PMID 40028035, 2025). "Preclinical studies have shown that combining EZH2-targeting agents with PD-1 inhibitors increases infiltration of immune cells into the tumor and extends survival, with clinical trials currently evaluating these effects." (PMID 40661151, 2025). "When specificially examining the tumor samples alone, we found that the cycling HepT population expressed high levels of EZH2, SUZ12, and EED, along with cell cycle regulators MKI67, AURKB, ASPM, TOP2A, and HELLS." (PMID 40766612, 2025). "In RCC, EZH2 promotes tumor progression through various mechanisms, including the repression of E-cadherin, which enhances cell migration and invasion." (PMID 39858107, 2025). "The upstream role of EZH2 in autophagy regulation also proves the potential application of targeted EZH2 in tumor therapy." (PMID 40028035, 2025). "Recent findings indicate that NEAT1 is upregulated in GC and that its overexpression can act as a scaffold to influence EZH2 expression, thereby affecting tumor invasion and metastasis." (PMID 41312360, 2025). "Inhibition of EZH2 appears to diminish tumor proliferation and metastasis in both in vitro and in vivo models." (PMID 41440218, 2025). "Another cell cycle regulator, EZH2, which is involved in epigenetic silencing of tumor‐suppressor genes by H3K27 methylation was identified as a putative direct target of TCF4." (PMID 39119816, 2025). "EZH2 knockout disrupts stem cell maintenance, triggers differentiation/apoptosis in mice, and inhibits tumor growth." (PMID 40756901, 2025). "In summary, treatment with the EZH2 inhibitor UNC1999 in combination with the ferroptosis inducer erastin promotes tumor ferroptosis in vivo and in vitro." (PMID 41372608, 2025). "Combination therapy targeting RSK4 (with the inhibitor BI-D1870) and EZH2 significantly inhibited tumor progression and improved survival in an orthotopic xenograft model." (PMID 40565099, 2025). "Given that NRP1 is involved in tumor progression across various cancer types, our study identified synchronous changes and positive correlation between EZH2 and NRP1 in CRC." (PMID 40314246, 2025). "We showed that EZH2 inhibition promotes DNA damage in epithelioid and rhabdoid tumor cells, at least in part via its induction of piggyBac transposable element derived 5 (PGBD5)." (PMID 40794452, 2025). "The upregulation of EZH2 is observed in various aggressive cancers, designating it as a driver oncogene for tumour growth." (PMID 39779467, 2025). "Strikingly, in both datasets we observed an increase in transcriptional heterogeneity, as measured by the mean distance between cells in each sample, in the mouse or human tumor samples expressing mutant-EZH2 compared to cells expressing the WT gene." (PMID 40504770, 2025). "Tazemetostat acts as an EZH2 inhibitor by blocking the EZH2 methyltransferase activity which leads to gene reactivation and tumor growth suppression in specific cancers." (PMID 40959208, 2025). "Scutellarein has been confirmed that it inhibits tumor growth and metastasis in ovarian cancer by regulating the EZH2/FOXO1 signaling pathway." (PMID 40271060, 2025). "MiR-34a and miR-200c can also act as tumor suppressors by directly regulating EZH2 levels in breast and in lung cancers, respectively." (PMID 41595461, 2025).
tumor (continued). "In summray, EZH2 inhibitor enhances tumor response to chemoimmunotherapy through DPP4-sICOSL pathway." (PMID 40708008, 2025). "The observed transcriptomic and protein alterations suggest that TCL tumor cells upregulate H3K27me3 primarily through EZH2 as a mechanism to resist HDAC inhibitors." (PMID 40659662, 2025). "Combining EZH2 degrader with anti-PD-1 significantly enhanced anti-tumor effects compared to monotherapy." (PMID 40308579, 2025). "Research studies show that incorporating EZH2 inhibitors with anti-PD-1/PD-L1 therapies significantly improves BC treatment results and decreases tumor worry." (PMID 40313963, 2025). "In detail, LINC-PINT, by directly recruiting EZH2, affects in vivo tumor growth in a xenograft model; GAS5 inhibits cell apoptosis and oxidative stress by recruiting E2F4 that reduces EZH2 expression." (PMID 40282449, 2025). "Targeting EZH2 with specific inhibitors is being investigated as a strategy to manage advanced PCa, given its role in promoting tumor growth and resistance to conventional therapies." (PMID 41402347, 2025). "In cancer context, during glioblastoma progression, EZH2 inhibition has been shown to reduce tumor cell proliferation, inhibiting abnormal angiogenesis and immunosuppressive signaling." (PMID 40723311, 2025). "Additionally, EZH2 influences immune escape mechanisms by suppressing antigen presentation, boosting regulatory T-cell activity, and attracting immunosuppressive cells including myeloid-derived suppressor cells (MDSCs) and tumor-associated macrophages (TAMs) 31-33." (PMID 41209556, 2025). "miR-101 and miR-26a can downregulate histone methyltransferase EZH2, reducing H3K27me3 levels and reactivating the transcription of tumor suppressor genes, thereby enhancing T cell activation and anti-tumor immune responses." (PMID 41394878, 2025). "In contrast, HepG2 and HUH7 cells, which resemble HC-NOS and HCC phenotypes, retained partial chemoresistance, suggesting tumor-type-specific mechanisms of EZH2 dependency." (PMID 40766612, 2025). "EZH2 activates the Notch signaling pathway and stimulates the secretion of effector cytokines that promote the survival of tumor-infiltrating CD8+ T cells." (PMID 39858465, 2025). "Numerous studies have shown that transcription of many tumor suppressor genes is repressed by EZH2 in malignant tumors, suggesting that EZH2 dysregulation plays a key role in carcinogenesis." (PMID 39850359, 2025). "Treatment with 50 μM TMZ significantly reduced the number of EZH2-positive cells in the U87 tumor, and this effect was substantially more significant than that of the combination." (PMID 40725030, 2025). "Collectively, These findings collectively suggest that NCTD exerts its anti-tumor effects via directly targeting to EZH2 and modulating the interaction between EZH2 and PP1, thereby potentially influencing tumor progression pathways in HCC." (PMID 40271060, 2025). "We identified the new mechanism about how EZH2 mediated tumor immune evasion, and also validated the effective combination of EZH2 inhibitors and chemoimmunotherapy." (PMID 40708008, 2025). "Epigenetic regulators such as EZH2 are also upregulated in UM, suppressing tumor-suppressor genes and inhibiting T-cell infiltration—a phenomenon recently identified as potentially targetable by specific therapies." (PMID 40661151, 2025). "The EZH2-associated lncRNAs are known to interact with histone methyl transferase EZH2 to promote cell proliferation, tumor progression, and cancer metastasis." (PMID 40243914, 2025). "EZH2 can regulate the innate and adaptive immune systems of the tumor microenvironment, EZH2 was a driver of resistance to immunotherapies." (PMID 40959108, 2025). "As the catalytic subunit of Polycomb Repressive Complex 2 (PRC2), EZH2 mediates H3K27me3, silencing tumor suppressor genes while promoting cell proliferation, migration, and immune evasion." (PMID 41029427, 2025).
tumor (continued). "For instance, EZH2’s dual role in suppressing tumor suppressor genes (e.g., CDKN1A, NLRP3) while activating pro-survival signals (e.g., Snail/EGFR) highlights its adaptability as a molecular switch in resistance trajectories." (PMID 40701777, 2025). "For example, the histone methyltransferase EZH2 has been shown to contribute to resistance by silencing tumor immunogenicity and antigen presentation, particularly during T cell-targeting therapies." (PMID 40739089, 2025). "Conversely, combining EZH2 and DNA methyltransferase inhibitors with PD-L1 blockade therapy enhances immune cell infiltration and suppresses tumor growth." (PMID 40042761, 2025). ": Patients with confirmed marker-tumour dependency are allocated to rationally designed combination therapies involving HPTM inhibitors (e.g. EZH2 inhibitors with ICIs or cytotoxic agents)." (PMID 40968252, 2025). "DNMT, HDAC, and EZH2 inhibitors can reopen immune gene loci, restore antigen presentation, and reinitiate T-cell infiltration, transforming an immune-cold tumor into a partially inflamed state." (PMID 41341594, 2025). "Prior work has demonstrated the tumor-suppressive effect of miR-138-5p through regulation of EZH2 and CCND1 in other cancers." (PMID 40869426, 2025). "In vivo, EZH2 overexpression significantly increased tumor volumes and weights in xenografts derived from HN6 cells with SLC31A1 knockdown, correlating with increased expression of the proliferation marker Ki67." (PMID 40719074, 2025). "As the catalytic subunit of the polycomb repressive complex 2 (PRC2), EZH2 mediates tri-methylation of histone H3 at lysine 27 (H3K27me3), resulting in transcriptional repression of tumour-suppressor genes and other regulatory elements." (PMID 40310411, 2025). "Our findings demonstrated that the protein expression of EZH2 in tumor cell lines was significantly higher than that in normal T cells, accompanied by increased levels of H3K27me3." (PMID 40659662, 2025). "Preclinical studies have shown that EZH2 inhibition can reduce tumor growth and metastasis by reversing EZH2-mediated gene silencing." (PMID 40191732, 2025). "Overexpression of the epigenetic regulator enhancer of zeste homolog 2 (EZH2) contributes to HB tumor growth and metastasis." (PMID 40766612, 2025). "Knockdown or depletion of EZH2 in tumor cells significantly enhanced the inhibitory effects of paclitaxel, docetaxel, and cisplatin on tumor cells, leading to a striking reduction in NRP1 levels." (PMID 40314246, 2025). "Particular focus is placed on aberrant DNA methylation (e.g., hypermethylation of CDKN2A, RASSF1A) and altered histone modifications (e.g., EZH2‐mediated silencing) as indicators of tumor heterogeneity and evolution." (PMID 40959208, 2025). "For instance, persistent H3K27me3 marks—which reflect transcriptional repression of tumor suppressor genes mediated by EZH2/PRC2 activity—provide a direct mechanistic rationale for combining EZH2 inhibitors with DNA-demethylating agents." (PMID 41199817, 2025). "Consistent with our findings that USP22 protects EZH2 from ubiquitination-mediated degradation, both USP22 and EZH2 proteins were highly expressed and positively correlated in tumor tissues compared with adjacent normal tissues." (PMID 41252204, 2025). "Immunohistochemical staining for PD-L1 (clone 22C3) and EZH2 was performed on tumour samples, and their expression levels were assessed." (PMID 40310411, 2025). "Here, the ETS like transcription factor 4 facilitates the interaction between SNHG22 and EZH2, promoting tumor cell survival and proliferation by upregulating NOTCH1 expression." (PMID 40042761, 2025). "In contrast, EZH2 knockdown resulted in tumours with well-differentiated epithelial cells characterised by keratin formation and a less aggressive and more epithelioid phenotype." (PMID 41614754, 2025).